RNU6-651P (RNA, U6 small nuclear 651, pseudogene)
Gene: Small nuclear RNA gene on chromosome 2 (201,646,716 to 201,646,820, forward strand). Ensembl gene ENSG00000222972.
Homologues: Orthologues: chimpanzee U6 (100% identical), macaque U6 (92% identical), dog U6 (77% identical), guinea pig U6 (76% identical), rabbit U6 (76% identical), rat LOC120097655 (75% identical), pig U6 (70% identical), rabbit U6 (70% identical). Paralogues in human: RNU6-73P (81% identical), RNU6-838P (79% identical), RNU6-1089P (78% identical), RNU6-1145P (78% identical), RNU6-274P (78% identical), RNU6-38P (78% identical), RNU6-41P (78% identical), RNU6-477P (78% identical), RNU6-110P (77% identical), RNU6-1214P (77% identical), RNU6-1332P (77% identical), RNU6-16P (77% identical), and 1286 more.